INS (insulin)
Diseases named in the same sentence as INS in open-access papers (continued):
Sharing a sentence is not in itself a finding about the gene and the disease.
Insulin resistance (continued). "Taken together, our results demonstrated that MIFP1G/P1G ameliorated HFD-induced insulin resistance via affecting insulin signaling pathway." (PMID 32265835, 2020). "Ramadan intermittent fasting decreased adiponectin and increased leptin, LAR, insulin, and insulin resistance in both Type 2 DM and FDRs as well as decreased GH in both FDRs and healthy controls and increased hs-CRP in healthy controls." (PMID 32775407, 2020). "During the second half of pregnancy, insulin resistance is characterized by severely high levels and insulin secretion increases approximately by 200 to 250%, in order to maintain euglycemic status." (PMID 32646482, 2020). "Although some patients can compensate for insulin resistance by increasing insulin secretion, defects in insulin secretion are common." (PMID 31925336, 2020). "After using insulin sensitizers to alleviate insulin resistance, the depressive behaviour of obese animals was alleviated." (PMID 32281722, 2020). "Studies on jejunal proteins from db/db mice showed impaired muscle insulin signaling, leading to insulin resistance." (PMID 32432228, 2020). "The belief that this product reflects insulin resistance is necessarily based on the assumption that insulin signalling alone quantitatively determines glucose level in a fasting steady state." (PMID 33365205, 2020). "Insulin resistance, commonly observed in patients with obesity, affects multiple organs, including the adipose tissue, muscle, and liver, and attenuates insulin signaling pathways." (PMID 33381523, 2020). "In line with this, TGFβ/SMAD3 signalling regulates insulin transcription in pancreatic islet β-cells, whereas SMAD3 deficiency in mice protects against insulin resistance and type 2 diabetes during high-fat-diet-induced obesity." (PMID 32722512, 2020). "Compared to the STD group, mice induced to obesity by the HFD exhibited higher levels of blood serum glucose and insulin, with a consequentially higher insulin resistance index HOMA-IR." (PMID 33489104, 2020). "It is a diagnosis in which the pancreas produces enough insulin but the body cannot use the insulin effectively, a condition called insulin resistance." (PMID 32872226, 2020). "First of all, the definition and measurement of insulin resistance using steady state glucose and insulin levels needs to be questioned." (PMID 33365205, 2020). "With the deepening of the research, GDM can induce changes in the levels of various factors in the body and act on islet cells to damage insulin, resulting in insulin resistance." (PMID 33083291, 2020). "As mediators of insulin action, myoIns, d-chiro-inositol, and IP6 have been shown to consistently decrease insulin resistance and to improve insulin sensitivity." (PMID 33139672, 2020). "The pathology of insulin-resistance lies in the high levels of insulin required to achieve these mildly elevated glucose levels." (PMID 32153503, 2020). "Nevertheless, in both male and female offspring weaned to control diet, the maternal fat-1 transgene conferred some protection from insulin resistance, where WT-HF offspring displayed elevated glucose levels during the insulin tolerance test." (PMID 32183350, 2020). "Insulin resistance is a systemic disorder affecting several insulin-regulated pathways and many organs." (PMID 33551987, 2020). "Fasting glucose and insulin levels and homeostatic model assessment of insulin resistance (HOMA–IR) in BBR-treated mice were reduced significantly (p < 0.05)." (PMID 33390968, 2020). "Insulin resistance has a major role in the pathogenesis of diabetic dyslipidemia as there is evidence of increased release of free fatty-acid from insulin resistance fat cells." (PMID 32968405, 2020). "It has been reported that ER stress-impaired insulin signaling leads to systemic insulin resistance, hyperglycemia, and hyperinsulinemia." (PMID 32375323, 2020). "E2 is known to protect women from insulin resistance, and insulin signaling is mandatory for normal HSR)." (PMID 32690985, 2020).
Insulin resistance (continued). "Previous studies have used upper and lower limits of fasting insulin to identify those with insulin resistance." (PMID 32375229, 2020). "miR-17 is a positive regulator, whereas miR-200a is a negative regulator of insulin signaling in skeletal muscle, and both miRNAs have the potential to become therapeutic targets for preventing and treating insulin resistance or type 2 diabetes." (PMID 32802189, 2020). "Insulin requirements typically increase into the third trimester due to increasing hormonal levels leading to insulin resistance as well as pancreatic beta cell dysfunction." (PMID 32117839, 2020). "Our study demonstrated that TyG index’s predictive ability was also higher than these two sets of indices, including lipid profiles of TG and HDL-C, and indices of non-insulin-based insulin resistance of TG/HDL-C and Mets-IR." (PMID 33059672, 2020). "High levels of circulating glucose can result from defective insulin secretion, insulin resistance, or both." (PMID 33329397, 2020). "Since inositols are efficient insulin sensitizers, these compounds act on the primal causes of PCOS symptoms on molecular level (namely, they prevent the insulin-resistance which constitutes a key factor in mechanisms of PCOS pathogenesis)." (PMID 32992734, 2020). "In general, the development of T2DM begins when the metabolic demand for insulin is greater, due to peripheral insulin resistance." (PMID 32283715, 2020). "We followed the development of enhanced insulin secretory response in normal dogs, demonstrating that the hyperbolic relationship is a dynamic one, as insulin response increased in proportion to insulin resistance." (PMID 33658981, 2020). "The results of the effect of ovariectomyand exogenous estradiol on blood glucose and insulin levelsand the index of insulin resistance in females correspond toexisting data." (PMID 33659826, 2020). "Phosphorylation of IRS-1 at serine sites and decreased phosphorylation of AKT result in disrupted insulin signaling and induction of insulin resistance." (PMID 31679138, 2020). "For cluster profiling, we additionally used indexes of metabolism mechanisms (e.g., tissue-specific insulin resistance, insulin clearance, and insulin secretion), non-alcoholic fatty liver disease (NAFLD), and glomerular filtration rate (GFR)." (PMID 32785111, 2020). "In conclusion, this study shows that miR-185 is down-expressed in the ovary of PCOS rats, and its overexpression can attenuate insulin resistance, high serum insulin level and ovarian histological lesion in PCOS." (PMID 32760272, 2020). "A previous study found that short-term intensive insulin therapy improves pancreatic β-cell function, insulin resistance, and lipid parameters in patients newly diagnosed with T2DM." (PMID 32566685, 2020). "Insulin resistance refers to a state of weakened insulin response, which is a common feature of T2D, obesity, and hypertension." (PMID 32982723, 2020). "The results of one study showed that when intravenous ammonia was infused in dogs, hyperglycemia and increased plasma insulin concentrations occurred and it suggested that hyperammonemia induces insulin resistance." (PMID 32405361, 2020). "The findings indicate that rats at 7 and 12 months of age showed decreased insulin responsiveness in reducing blood glucose levels and developed insulin resistance when compared with rats at 2 months of age." (PMID 32679813, 2020). "The β-cells respond to insulin resistance by increased insulin production although, at some point, the cells become exhausted with resulting hyperglycemia when the production of insulin does not match the increased insulin demand." (PMID 32093016, 2020). "This gap was also observed in our lab, attributed to decreased insulin clearance inherent in type 2 diabetes and to acquired insulin resistance in hyperglycemia among type 1 diabetes subjects." (PMID 32308680, 2020).
Insulin resistance (continued). "Since insulin resistance is an accepted contributor to a worsening AD condition, some strategies have been designed in order to restore insulin signaling in the brain." (PMID 32825356, 2020). "It is noteworthy that insulin release will elevate to compensate insulin resistance so that to maintain euglycemia, and subsequently falls down to elevate the plasma glucose levels, making it a very complicated physiological process in organism." (PMID 32928312, 2020). "Birds with low MEF2C expression showed an insulin resistance with significantly higher blood glucose levels after 3 h of fasting and had similar insulin concentration." (PMID 33370292, 2020). "Deteriorated insulin-mediated substrate switching is the best example of metabolic inflexibility and it has a central role in obesity and in the development of insulin resistance." (PMID 32235294, 2020). "Residual glucose and insulin signaling-related proteins were detected and the mechanisms associated with the SIRT1/FOXO1 signaling pathway in insulin resistance explored." (PMID 32280711, 2020). "The pancreatic β-cell increases insulin production for glucose disposal in the early stage of insulin resistance; however, extended hyperglycemic conditions eventually lead to type 2 DM." (PMID 33255372, 2020). "Differential methylation in 3,787 genes involved in insulin secretion and pancreas function; improved insulin resistance and fat reduction." (PMID 33585535, 2020). "We also determined that the consumption of a WSD induced systemic insulin resistance, while CR restored normal insulin sensitivity in rhesus macaques." (PMID 32085416, 2020). "In the EMERALD (Effects of Metformin on CardiovasculaR function in AdoLescents with Type 1 diabetes) trial, metformin therapy as add-on to insulin improved insulin resistance and vascular health." (PMID 33010807, 2020). "Instead, HOMA insulin resistance, a well-accepted measure of hepatic insulin sensitivity, appeared to markedly improve when breakfast was delayed by 4 h, at least in females." (PMID 32707917, 2020). "Plasma metabolic profile evidenced that the HFF diet was able to induce systemic insulin resistance, with higher fasting glucose and insulin levels and increased Homeostasis model assessment (HOMA) index." (PMID 31991770, 2020). "The pathogenesis of insulin resistance in a lean patient has been proven to be the same as what is seen in an obese individual, but most studies confirm more severe functional insulin secretory defects in lean individuals compared to the obese phenotype." (PMID 32399348, 2020). "In our study, taurine did not directly influence the serum glucose concentration, but to some extent, it normalized the serum insulin and insulin resistance index HOMA-IR in the rats fed the high-fat diet." (PMID 32172503, 2020). "The primary outcome will be IR (using recognized methods such as homeostasis model assessment of insulin resistance), secondary outcomes will be blood pressure, fasting plasma glucose, fasting plasma insulin." (PMID 32541513, 2020). "In particular, insulin resistance contributes to compensatory hyperinsulinemia via taxation on the pancreatic beta-cells to secrete insulin." (PMID 32849302, 2020). "In order to adapt to the insulin resistance and the reduction of sensitivity during pregnancy, insulin secretion increases." (PMID 32904578, 2020). "Insulin resistance, fasting insulin level, insulin-like growth factor (IGF), and lifestyle intervention were also found to be significantly associated with WMH." (PMID 33408693, 2020). "Only the combination of a balanced diet together with the intake of orange juice lowered insulin and insulin resistance." (PMID 32669965, 2020). "In obese mice, increased levels of macrophages in adipose tissue release this adipokine, which inhibits insulin-activated glucose transport to the tissues, inducing insulin resistance." (PMID 33081064, 2020).
Insulin resistance (continued). "Regarding glucose homeostasis, TNFi therapy reduced insulin levels and improved insulin resistance and insulin sensitivity." (PMID 32370139, 2020). "The results clearly showed that glucose tolerance and insulin tolerance were impaired, and hyperglycemia developed in EtOH-fed mice, which are the characteristics of insulin resistance." (PMID 32508647, 2020). "The HOMA-IR is a mathematical method that measures insulin resistance using fasting serum insulin and fasting plasma glucose values." (PMID 32643339, 2020). "Factors produced by the placenta such as human placental lactogen, placental growth hormone, and TNF-α progressively rise during pregnancy to induce peripheral insulin resistance through disruption of intracellular insulin signaling." (PMID 32977673, 2020). "In diseases like type 2 diabetes, amelioration of insulin resistance and reduction of insulin levels recover the fibrinolytic function." (PMID 32752277, 2020). "Insulin resistance in obese mice through ER stress-mediated JNK pathway is induced by the phosphorylation of insulin receptor substrate 1 (IRS1), which impairs insulin action and causes insulin resistance." (PMID 32942585, 2020). "Elevation of semi-fasting and fasting blood glucose levels is indicative of insulin resistance, which is further evaluated by performing oral glucose tolerance and insulin tolerance tests and analyzing a body of blood biomarkers." (PMID 33322303, 2020). "Patients with LADA were more often on insulin treatment and had worse beta cell function but lower degree of insulin resistance." (PMID 30656477, 2020). "Plasma levels of insulin were also significantly increased in male offspring of selenium-deficient dams at PN180, which is suggestive of insulin resistance." (PMID 31968625, 2020). "Pancreatic islet β cells, therefore, have to secrete more insulin to compensate for insulin resistance, resulting in hyperinsulinemia which leads to dysfunction of β cells and T2DM." (PMID 32582032, 2020). "For patients in the intensive care unit (ICU), the prevalence of hyperglycemia (>180 mg/dl) is 32.2% because of decreased responsiveness to the metabolic actions of insulin, named insulin resistance." (PMID 32679813, 2020). "The defect in the insulin signaling pathway in adipose tissue and skeletal muscles reduces their sensitivity to insulin, leading to the development of insulin resistance." (PMID 32523023, 2020). "It is widely accepted that increasing body adiposity is related to elevated insulin resistance, and in turn, the insulin resistance compensatory response increases insulin levels and decreases insulin sensitivity under both basal and stimulated conditions." (PMID 32029228, 2020). "Fasting blood glucose, serum insulin and insulin resistance in the different studied groups represented as mean ± SEM." (PMID 32544194, 2020). "Insulin resistance (IR) is a pathological condition in which the action of insulin, which aims to facilitate glucose uptake and metabolism in peripheral tissues, is reduced." (PMID 32774364, 2020). "Insulin resistance calculated using insulin levels (HOMA-IR) increased in the TB-DM patients after the start of anti-TB treatment." (PMID 33287713, 2020). "Mechanistically, 2.4 competitively inhibited PTP1B via binding to the catalytic site through hydrogen bonds, activated insulin signaling in an insulin-independent manner, and ameliorated insulin resistance through enhancing insulin sensitivity." (PMID 32759739, 2020). "PLSR analysis also revealed changes in cytokine expression associated with high insulin levels and insulin resistance in our mixed AD-T2D model, and both insulin and insulin resistance are major contributors to central complications in AD and T2D." (PMID 31992349, 2020). "The lipid mediator leukotriene with increased production during inflammation plays an essential role in the development of insulin resistance and mediates β-cell destruction resulting in reduced insulin production." (PMID 32093765, 2020).
Insulin resistance (continued). "Pregnant Fxr−/− mice displayed significant glucose intolerance and insulin resistance, as well as diminished secretion of insulin, compared to wild type pregnant mice." (PMID 32661285, 2020). "IL6 has also been shown under some circumstances to stimulate insulin secretion, whilst subsets of islet macrophages have been reported to simultaneously impair insulin secretion but promote beta-cell proliferation in models of insulin resistance." (PMID 32599074, 2020). "Hyperinsulinemia from adiposity-dependent insulin resistance can further sensitize thecal cells to LH stimulation and, in doing so, disrupt follicle development through synergistic actions of insulin and LH on enhancing ovarian theca cell androgen production." (PMID 32310267, 2020). "Clinical studies have suggested that the pathogenesis of type 2 diabetes is usually considered as insulin resistance in which pancreatic β-cells increase their mass and insulin secretion as the initial step." (PMID 32775460, 2020). "Insulin resistance is of particular interest as defective insulin signalling in the brain contributes to the accumulation of amyloid beta (Aβ) and tau protein, presenting a pathophysiological link between Alzheimer’s disease (AD) and type 2 diabetes (T2D)." (PMID 32283762, 2020). "It is generally accepted that abnormalities in the insulin signaling pathway are responsible for the development of insulin resistance that is characterized by reduced reaction of target cells to circulating insulin." (PMID 32932777, 2020). "Obesity-induced insulin resistance presumably leads to hyperglycemia, leading to increased synthesis of insulin." (PMID 32842547, 2020). "Obesity is well-known to modify the glucose-insulin axis, as it often goes hand in hand with hyperinsulinemia and insulin resistance." (PMID 33154737, 2020). "It was noted that a higher dose of cells needed to be injected in the insulin-resistant patients for similar outcomes to the non-insulin resistant group showing a reduced efficacy in insulin resistance." (PMID 33364119, 2020). "GDM is characterized by even more pronounced insulin resistance, accompanied by an insufficient increase in insulin production to overcome insulin resistance." (PMID 32080229, 2020). "High‐fat high‐energy diets contribute to development of insulin resistance and type 2 diabetes, and n‐3PUFA have been proposed to improve insulin sensitivity." (PMID 32845565, 2020). "Insulin resistance is defined as an attenuated effect of insulin on blood glucose homeostasis, primarily by less efficient export of glucose from the blood into skeletal muscle, adipose, and liver tissue." (PMID 32819363, 2020). "An investigation using an animal model demonstrated that oral intake of AGEs impaired insulin uptake and induced insulin resistance by altering insulin receptor signal transduction." (PMID 33148181, 2020). "Many recent studies have indicated that impaired hippocampus insulin signaling impairs the memory and other executive functions, attributing to the decline of insulin signaling and concurrent development of insulin resistance." (PMID 32365816, 2020). "Peripheral insulin resistance leads to a rise in insulin demand and triggers pancreatic β-cell adaptation by increasing both β-cell mass and function to release sufficient insulin and therein maintain normoglycemia." (PMID 32150819, 2020). "Insulin resistance, defined at the molecular level by defective signalling in response to insulin, plays an important role in metabolic disorders such as obesity and type II diabetes." (PMID 32249683, 2020). "Studies of the underlying mechanisms have shown that skeletal muscle oxidative stress can impair insulin signaling and induce insulin resistance." (PMID 32082422, 2020). "Yet, fasting glucose shows stronger statistically significant correlation with metabolites, and with insulin and insulin resistance, than HbA1c during childhood." (PMID 32984398, 2020).